FCRL2 (Fc receptor like 2)
Description:
May have an regulatory role in normal and neoplastic B cell development.
Synonyms: FcRH2; CD307b; IFGP4; IRTA4; SPAP1; SPAP1A; SPAP1B; SPAP1C
Tractability: Antibody: UniProt places it where antibodies can reach, with high confidence; UniProt predicts a signal peptide or a membrane-spanning region; its Gene Ontology location is reachable by antibodies, with medium confidence. PROTAC: ubiquitination databases record sites on it; its protein half-life has been measured.
Gene: Protein-coding gene on chromosome 1 (157,745,733 to 157,777,269, reverse strand). Ensembl gene ENSG00000132704.
Subcellular location: Cell membrane
Gene Ontology:
Molecular function: protein binding; protein phosphatase binding; signaling adaptor activity; transmembrane signaling receptor activity
Biological process: cell surface receptor signaling pathway; cell-cell signaling; immune response
Cellular component: cell surface; external side of plasma membrane; membrane; plasma membrane
Genetic constraint (gnomAD): Loss-of-function variants: 50 observed, 61.83 expected, observed/expected ratio (o/e) 0.81, 90% interval 0.64 to 1.02. The upper end of that interval is the gene's LOEUF score, 1.02, which puts it in group 4 of 6, group 1 being the genes least tolerant of losing a copy. Missense variants: 642 observed, 619.16 expected, observed/expected ratio (o/e) 1.04, 90% interval 0.97 to 1.11. Synonymous variants: 248 observed, 240.8 expected, observed/expected ratio (o/e) 1.03, 90% interval 0.93 to 1.14.
Homologues: Orthologues: chimpanzee FCRL1 (98% identical), macaque FCRL2 (91% identical), rabbit FCRL2 (70% identical), dog FCRL2 (65% identical). Paralogues in human: FCRL3 (55% identical), FCRL5 (48% identical), FCRL1 (46% identical), FCRL4 (38% identical), FCRL6 (29% identical), PECAM1 (20% identical), FCRLB (16% identical), FCRLA (15% identical), FCGR1A (15% identical), FCGR2B (10% identical), MILR1 (9% identical), FCGR3A (8% identical), and 5 more.
Diseases named in the same sentence as FCRL2 in open-access papers:
FCRL2 is named in the same sentence as 19 diseases in open-access papers, as found by Europe PMC text mining. Sharing a sentence is not in itself a finding about the gene and the disease. The quoted sentences say what the papers report.
chronic lymphocytic leukemia (3 papers, 2019 to 2024). "FCRL2 expression was previously reported as a prognostic factor in chronic lymphocytic leukemia." (PMID 31839882, 2019). "Furthermore, FCRL2 expression predicts clinical progression in chronic lymphocytic leukemia." (PMID 35783274, 2022).
autoimmune disorders (1 paper, 2020). "In a previous study, two other autoimmune disorders, HT and GD, showed a significant decrease in the FCRL1 gene expression level but a considerable increase in FCRL2 and FCRL4 genes expression with compare to the corresponding healthy controls." (PMID 34466580, 2020).
breast tumors (1 paper, 2025). "In metastatic breast cancer, decreased expression of FCRL2 mRNA was observed in brain metastatic tissues compared to primary breast tumors, and its expression in primary tumors was correlated with patient survival." (PMID 39869563, 2025).
dilated cardiomyopathy (1 paper, 2016). Cardiomyopathy which is characterized by dilation and contractile dysfunction of the left and right ventricles. "This is consistent with the GEO database at NCBI9, which suggests that FCRL2 is upregulated in patients with AF and dilated cardiomyopathy." (PMID 27877193, 2016).
heart failure (1 paper, 2016). Inability of the heart to pump blood at an adequate rate to meet tissue metabolic requirements. "Rare variant analysis in these regions uncovered two genes related to heart failure, TTN (P = 5.5 × 10-2) and HSD3B1 (P = 3.9 × 10-2) and one gene with unknown cardiac function FCRL2 (P = 2.8 × 10-4)." (PMID 27877193, 2016).
Hepatitis C (1 paper, 2020). "Markedly high FCRL2, FCRL3, and FCRL5 were identified in the context of Hepatitis C vaccination." (PMID 32747654, 2020).
lymphoblastic leukemia (1 paper, 2021). "Fc Receptor Like 2 (FCRL2) is a member of the immunoglobulin receptor superfamily that is involved in the development of lymphoblastic leukemia by immunomodulating B cell function." (PMID 33441161, 2021).
cancer (4 papers, 2021 to 2025). A tumor composed of atypical neoplastic, often pleomorphic cells that invade other tissues. "A comparison with a recently published list of cell-specific marker genes of tumor-infiltrating leukocytes (TILs) derived from pan-cancer data showed the presence of the B-cell marker FCRL2 and the natural killer cell marker IL21R." (PMID 33980253, 2021). "F2RL1, also known as Fc receptor-like 2, has been studied in the context of cancer." (PMID 39869563, 2025).
tumor (4 papers, 2020 to 2023). "Additionally, from 8 reported markers reflecting B-cell level in tumor environment, some of them, such as PNOC, FCRL2, CD19, were found to have different degrees of impact on poorer prognosis on overall survival of ccRCC cohort." (PMID 37908350, 2023).
blood cancers (1 paper, 2024). "Among the proteins associated with risk of haematological cancers, we identified associations with risk of multiple blood cancers for members of the FC-receptor protein [FCRL1, FCRL2, FCRL3, FCRL5, FCRLB] and TNF receptor families [TNFRSF4, TNFRSF9, TNFRSF13B, TNFRSF13C, TNFSF13B, TNFSF13]." (PMID 38750076, 2024).
FCRL2 also shares sentences with these, for which no sentence is quoted: lymphoma (2 papers); multiple myeloma (2); Arthritis (1); breast carcinoma (1); colon cancer (1); Hashimoto thyroiditis (1); infection (1); leukaemia (1); thyroid (1).